ROCK1 (Rho associated coiled-coil containing protein kinase 1)
Diseases named in the same sentence as ROCK1 in open-access papers (continued):
Sharing a sentence is not in itself a finding about the gene and the disease.
cardiac hypertrophy (13 papers, 2015 to 2025). "It has been reported that cleavage of ROCK1 and RhoA/ROCK1-Bax signaling promote apoptosis associated with myocardial hypertrophy and heart failure." (PMID 35370759, 2022). "For example, TAC-induced cardiac hypertrophy and fibrosis were promoted in cardiac-specific ROCK1-deficient mice." (PMID 34462460, 2021). "Consistent with this, ROCK1 deficiency might have beneficial effects in preventing the transition from cardiac hypertrophy to heart failure." (PMID 26635606, 2015). "There were no studies that exosomes let‐7g‐5p, let‐7f‐5p and miR‐148a‐3p targeted the Calm/MLCK/p‐MLC2 and Rhoa/ROCK1/p‐MLC2 signal pathway to induce myocardial hypertrophy." (PMID 41235503, 2025). "To investigate the role of ROCK1 in cardiac hypertrophy, we transfected H9c2 cells with ROCK1 siRNA." (PMID 34462460, 2021). "Our results indicate that protocatechuic acid acts via the ROCK1/Sp1/PKCγ axis and therefore has promising therapeutic potential as a treatment for cardiac hypertrophy." (PMID 34462460, 2021). "We demonstrated that protocatechuic acid attenuated cardiac hypertrophy by inhibiting the ROCK1–Sp1–PKCγ axis." (PMID 34462460, 2021). "We recently found that ROCK1 is a key molecule in mediating apoptotic signaling in cardiomyocytes under pressure overload and in genetically-induced pathological cardiac hypertrophy." (PMID 29560126, 2018). "Mice with a global ROCK1 deletion that underwent TAC to induce cardiac hypertrophy had reduced perivascular and interstitial cardiac fibrosis at 3 weeks, but not at 1 week after the banding." (PMID 26635606, 2015). "Both treatments led to a comparable increase in systemic blood pressure, left ventricular wall thickness and mass, and hypertrophy in haploinsufficient ROCK1 and wild type mice." (PMID 26635606, 2015). "A role for ROCK1 in cardiac hypertrophy and remodeling was also addressed using haploinsufficient ROCK1+/– mice, which were treated either with angiotensin II or NG-nitro-L-arginine methyl ester (L-NAME) to inhibit NOS." (PMID 26635606, 2015). "Global homozygous ROCK1–/– and heterozygous ROCK1+/– mice show beneficial effects such as decreased cardiac fibrosis without affecting pressure overload or angiotensin II-induced cardiac hypertrophy." (PMID 35043239, 2022). "However, our results clearly demonstrated that the knockdown of ROCK1 reduced the size of cardiomyocytes increased by isoproterenol treatment, suggesting that ROCK1 was involved in the pathogenesis of cardiac hypertrophy." (PMID 34462460, 2021). "Our data indicate that ROCK1, Sp1, and PKCγ are involved in the development of cardiac hypertrophy and, therefore, could be used as new therapeutic targets for cardiac hypertrophy." (PMID 34462460, 2021). "The observations describing the role of ROCK1 in cardiac hypertrophy are contradictory." (PMID 34462460, 2021). "We already know from rodent studies that Rho kinase is involved in bladder hyperactivity, but in addition, it was always the ROCK1 isoform that was identified to be up-regulated in rat decompensated detrusor hypertrophy or in altered detrusor contractility of diabetic rabbits." (PMID 26468005, 2015). "Interestingly, KO of ROCK1 reduced the induction of hypertrophic markers, suggesting that ROCK1 might at least be able to modify cardiac hypertrophy." (PMID 26635606, 2015). "Isoform-specific knockout mouse models revealed ROCK1 contributing to the pathogenesis of cardiac fibrosis and ROCK 2 in cardiac hypertrophy, respectively." (PMID 39779619, 2025). "In contrast to the proposed role of ROCK1 in cardiac fibrosis, ROCK2 was shown to be an important player in cardiac hypertrophy." (PMID 26635606, 2015). "With respect to the heart, findings in isoform-specific knockout mice argue for a role of ROCK1 and ROCK2 in the pathogenesis of cardiac fibrosis and cardiac hypertrophy, respectively." (PMID 26635606, 2015).
cardiac hypertrophy (continued). "Global ROCK1 deletion mice, as well as hemizygous ROCK1+/− mice, exhibited reduced cardiac fibrosis, and the development of cardiac hypertrophy was not affected after TAC or in response to angiotensin II treatment." (PMID 34462460, 2021). "In a model of Gαq overexpression, ROCK1 deletion attenuated left ventricular dilation and cardiomyocyte apoptosis, but did not prevent the development of cardiac hypertrophy." (PMID 32370294, 2020). "Other studies using ROCK1 and ROCK2 KO mice and ROCK inhibitors in various animal models indicate the involvement of ROCK in diabetic vasculopathy, ischemia/reperfusion injury, heart failure, cardiac hypertrophy, and fibrosis." (PMID 29749605, 2018). "In another transgenic model of Gαq overexpression, ROCK1 deletion attenuated left ventricular dilation, contractile dysfunction and cardiomyocyte apoptosis, but did not prevent the development of cardiac hypertrophy." (PMID 26635606, 2015). "Interestingly, in aortic constriction model, the cardiomyocyte‐specific deletion of ROCK2 suppressed the cardiac hypertrophy 78, while the ROCK1 haploinsufficiency did not prevent cardiac hypertrophy but reduced fibrosis under the same condition." (PMID 29749605, 2018). "Interestingly, ROCK1 deletion did not impair the development of cardiac hypertrophy." (PMID 26635606, 2015).
atherosclerosis (12 papers, 2013 to 2025). A disease characterized by the build-up of fatty material and calcium deposition in the arterial wall resulting in partial or complete occlusion of the arterial lumen. "As the RhoA/ROCK1 pathway is pivotal in atherosclerosis progression, and mitochondrial dysfunction is a recognized pathogenic mechanism of atherosclerosis, the relationship between the RhoA/ROCK1 pathway and mitochondrial dynamics has attracted our attention." (PMID 37278388, 2023). "Multiple research has demonstrated an association between the activation of the RhoA/ROCK1 pathway and the onset and progression of atherosclerosis." (PMID 37278388, 2023). "Additionally, RBP4 regulates the phenotypic transformation of vascular smooth muscle cells via the Ras homolog family member A/Rho-associated coiled-coil containing protein kinase 1 (RhoA/ROCK1) signaling pathway in atherosclerosis." (PMID 39981296, 2025). "Of note, Rnd3 seems to exhibit profound interaction in ECs directly through Rock1 or NF‐κB in atherosclerosis." (PMID 37743632, 2023). "Taken together, circ_UBR4/miR-107/ROCK1 pathway has a possible role in the development of atherosclerosis through modulation of proliferative ability, migration, and cell cycle transition of human VSMCs." (PMID 36177350, 2022). "ROCK1 is predominantly upregulated in macrophages that were activated and adherent to endothelial cells during atherosclerosis." (PMID 25889164, 2015). "Drugs that could inhibit the RhoA/ROCK1 pathway were expected to become new targets for treating atherosclerosis with P. gingivalis infection." (PMID 37278388, 2023). "Moreover, expression levels of circ_UBR4 and ROCK1 have been found to be increased in sera of patients with atherosclerosis, parallel with down-regulation of miR-107." (PMID 36177350, 2022). "One previous study demonstrated that the isoform ROCK1 is crucial for macrophage-mediated atheroma formation, indicating that the activation of ROCK is important in the inflammation process of atherosclerosis." (PMID 24716192, 2014). "Collectively, these findings highlight the distinct and context-dependent roles of ROCK1 and ROCK2 in pulmonary hypertension, cardiac remodeling, fibrosis, and atherosclerosis, underscoring their potential as differential therapeutic targets in cardiovascular diseases." (PMID 41377066, 2025). "In a lysophosphatidic acid-induced model, lack of ROCK2, but not ROCK1, decreases the migration and adhesion of monocytes to endothelial cells, a critical initiating event in the early development of atherosclerosis." (PMID 41377066, 2025). "The elevated level of ROCK1 inhibits eNOS activity, an effector substrate of ROCK, and NO levels, resulting in impaired endothelial function and vasodilation, thereby accelerating the progression of atherosclerosis." (PMID 37278388, 2023). "Additionally, we identified 4 new MMVD stage B2 targets (MDM2, ROCK1, RIPK1, and SNAP23) that have been studied in many cardiovascular diseases in human medicine, such as chronic heart failure, atherosclerosis, and diabetic cardiomyopathy." (PMID 38087280, 2023). "ROCK1 and ROCK2 appear to be widely expressed, with ROCK2 most abundant in smooth muscle and heart, suggesting an important role of this isoform in the pathogenesis of hypertension, atherosclerosis and cardiovascular disease." (PMID 23326532, 2013). "However, the specific regulatory mechanisms of ROCK1 and ROCK2 in ameliorating graft atherosclerosis remain unclear." (PMID 28050227, 2016).
fibrosis (11 papers, 2015 to 2024). the formation of excess fibrous connective tissue in an organ or tissue in a reparative or reactive process. "Therefore, this study provides new evidence that HPM ameliorates CD-associated intestinal fibrosis by inhibiting RhoA and ROCK1 proteins." (PMID 34840583, 2021). "Our accumulated data suggest that SLIT3 significantly regulates Ang II-induced cardiac fibrosis and fibroblast differentiation via the RhoA/ROCK1 signaling pathway." (PMID 38800023, 2024). "Unexpectedly, we found that the extent of cardiac fibrosis indicated by Masson’s trichrome staining was comparable in Rock1+/− and wild-type mice." (PMID 32178482, 2020). "Similarly, a recent study using aged rats showed that the RhoA/ROCK1/LIMK2/Cofilin pathway was involved in cavernosal fibrosis and ED caused by advanced age, suggesting that these factors might be novel targets in the treatment of age-related cavernosal fibrosis." (PMID 30870492, 2019). "One reasonable explanation for the effects on cardiac fibrosis in the different genetic ROCK1 mouse models is a positive feed-forward regulatory loop of ROCK1 and caspase-3." (PMID 26635606, 2015). "Inhibition of ROCK1 activation could be a potent therapeutic strategy for fibrosis-related diseases." (PMID 38711089, 2024). "Therefore, SLIT3 could significantly affect cardiac fibrosis and fibroblast differentiation through the RhoA/ROCK1 pathway." (PMID 38800023, 2024). "However, it is likely that ROCK1-induced cardiomyocyte death also contributes to cardiac fibrosis." (PMID 26635606, 2015). "The results showed thatFgf13 knockdown inhibited ROCK1 protein upregulation by depolymerizing microtubules, indicating that ROCK is involved in FGF13 regulation in cardiac fibrosis via microtubules." (PMID 38818580, 2024).
glaucoma (11 papers, 2009 to 2025). Increased pressure in the eyeball due to obstruction of the outflow of aqueous humor. "The variants of ROCK1 were associated with disease susceptibilities like cardiovascular diseases, cancers, autoimmune diseases, and glaucoma." (PMID 37683138, 2023). "In the context of glaucoma therapy, the CasRx system predominantly focuses on the RNA‐level knockdown of aquaporin 1 (Aqp1), β2‐adrenergic receptor (Adrb2), and Rho‐associated kinase 1/2 (Rock1/Rock2)." (PMID 40536333, 2025). "Third, while ITRI-ES pharmacological properties have been described in glaucoma models (showing intraocular bioavailability up to 24 h and selective ROCK1/2-MYLK4 inhibition), its pharmacokinetics in NMOSD optic neuritis remain untested." (PMID 41227356, 2025). "Here, the authors show that AAV-delivered CasRx to reduce the expression of Rock1 and Rock2 as well as Aqp1 and Adrb2 can significantly reduce intraocular pressure, ultimately delaying glaucoma progression in mice." (PMID 39080269, 2024). "Next, we evaluated the therapeutic effect on glaucoma using the CasRx system to interfere with the expression of the Rock1 and Rock2 genes, as well as the Aqp1 and Adrb2 genes, on two simulated glaucoma model mice." (PMID 39080269, 2024). "Using two different mouse models of glaucoma, we show that reducing the expression of Aqp1 and Adrb2 in the CB or Rock1 and Rock2 in the TM, significantly reduces IOP, protects retinal RGC cells and delays disease progression." (PMID 39080269, 2024). "Currently, marketed ROCK inhibitors approved for glaucoma treatment are Ripasudil (K-115; brand name: Glanatec) and netarsudil (AR-13324; brand name: Rhopressa), which target both ROCK1 and ROCK2." (PMID 38891764, 2024). "However, ripasudil which was used as a drug for the treatment of glaucoma in Japan was also one of the inhibitors of ROCK1 and ROCK2." (PMID 32252692, 2020). "Ripasudil, which was used for the treatment of glaucoma, was one kind of the inhibitor of ROCK1 and ROCK2, but whether ripasudil could relieve the LPS-induced inflammation and damage of RPE cells was not clear." (PMID 32252692, 2020). "ROCK1 and ROCK2 were expressed in many organs including the retina, while excessive expression of ROCK1 and ROCK2 caused many diseases in the eye, such as diabetic retinopathy and glaucoma." (PMID 32252692, 2020). "Ripasudil (also known as K115) is currently in clinical use as a topical treatment for glaucoma and ocular hypertension and is a more selective inhibitor of ROCK2 with IC50 of 0.051 μM for ROCK1 and 0.019 μM for ROCK239." (PMID 40253509, 2025). "Molecular docking, for instance, empowers researchers to predict the binding affinity and conformational preferences of potential therapeutic agents directed toward specific protein targets, as exemplified by the case of ROCK1 and ROCK2 in glaucoma." (PMID 37627868, 2023). "The expression of ROCK isoforms, ROCK1 and ROCK2, is recognized to occur in various ocular tissues and is also involved in the pathogenesis of several ocular diseases, including glaucoma, cataracts, corneal dysfunction, retinopathy and retinal dystrophy." (PMID 34298955, 2021). "And there is also study revealed that the ROCK1 and ROCK2 are expressed in the trabecular meshwork and ciliary muscle tissues of glaucoma patients." (PMID 32252692, 2020). "The molecular docking study was based on ligands with demonstrated biological action in the scientific literature (i.e., ripasudil and fasudil) and targeting key proteins (i.e., ROCK1 and ROCK2) identified as being involved in the modulation of glaucoma pathophysiological mechanisms." (PMID 37627868, 2023).
neuroblastoma (11 papers, 2012 to 2025). Neuroblastoma (NB) is the most common solid, extracranial childhood tumor. "The ROCK1/2 inhibitor RKI-1447 suppresses N-MYC, induces cell death, and synergizes with BET inhibitors in neuroblastoma." (PMID 40368918, 2025). "In neuroblastoma cells, MIR335 downregulates the ROCK1 and MAPK1 genes, involved in the non-canonical TGF-β pathways." (PMID 32582296, 2020).
Hypertension (10 papers, 2013 to 2025). The presence of chronic increased pressure in the systemic arterial system. "The notion that this isoform is implicated in arterial hypertension has launched substantial pharmaceutical interest in developing ROCK1 inhibitors as a new class of antihypertensive medication." (PMID 26468005, 2015). "ROCK1 isoform seems to be predominant in epithelial polarized cells and is involved in endothelial cell shape modification, while abnormal vascular activation of ROCK1 is involved in hypertension, stroke, and other cardiovascular diseases." (PMID 34452066, 2021). "ROCK-1 expression had a large increase in hypertension, while ROCK-1 expression decreased with age." (PMID 36313372, 2022). "Furthermore, a role for ROCK1 has been suggested in hypertension and increased ROCK2 expression has been described in preeclamptic human placentas." (PMID 25611484, 2015).
Cognitive impairment (9 papers, 2016 to 2025). Abnormal cognition is characterized by deficits in thinking, reasoning, or remembering. "The Rho-associated protein kinase 1 (ROCK1) protein level is elevated in mild cognitive impairment and AD, and its reduction by hemizygous knockout blunted the high amyloid levels seen in a mouse model of AD." (PMID 35890250, 2022). "ROCK1 downregulation in microglia promoted their lysosomal function and reduced their activation to an intermediate state, and eventually ameliorated the cognitive impairment of APP/PS1 mice." (PMID 39497162, 2024). "MTX-induced neurotoxicity and cognitive impairment could be attributed to the microglial activation and neuroinflammatory response in part through the miR-15a/ROCK-1/ERK1/2/CREB/BDNF cascade." (PMID 36943623, 2023). "Moreover, inhibition of microRNA-146a expression with antagomir not only reverses the protein levels and/or phosphorylation of crucial signaling pathway elements (ROCK1-PTEN-Tau) in the brain, but also partly attenuates associated cognitive impairment." (PMID 27221467, 2016). "Nevertheless, the correlations between the RhoA/ROCK1 and EGFR/PI3K/Akt signaling pathways and the key factors involved in the occurrence of surgery-induced cognitive impairment need further experimental verification." (PMID 39781463, 2025). "Inhibition of microRNA-146a expression with antagomir not only enhanced ROCK1 protein translation and PTEN phosphorylation, decreasing tau hyperphosphorylation, but also partly reversed cognitive impairment in 5xFAD mice." (PMID 27221467, 2016). "Genetically downregulating ROCK1 lowered its interference with TFEB, promoted TFEB nuclear distribution, lysosomal biogenesis and lysosome-mediated Aβ clearance, and eventually prevented pathological traits and cognitive deficits in APP/PS1 mice." (PMID 39497162, 2024).
heart failure (9 papers, 2014 to 2024). Inability of the heart to pump blood at an adequate rate to meet tissue metabolic requirements. "Altogether, ROCK1 represents a potential therapeutic target in preventing the anti-cancer drug doxorubicin-induced heart failure and possibly other drug-induced cardiotoxicity related heart failure." (PMID 29560126, 2018). "In heart tissues from patients with heart failure the cleaved ROCK1 fragment, as well as active caspase-3 was detectable, but was almost absent in normal hearts and in an equivalent cohort of patients with left ventricular assist devices." (PMID 26635606, 2015). "Others have reported increased ROCK1 expression in aorta from diabetic rats, and ROCK1 has been shown to play an important role in other forms of cardiac dysfunction, including heart failure." (PMID 24466133, 2014). "It is worth noting that the inhibition of ROCK1 deletion on actin cytoskeleton remodeling observed in this study is consistent with our previous in vivo observations that ROCK1 deletion inhibits cardiac remodeling and cardiomyocyte apoptosis in pathological heart failure." (PMID 24595357, 2014).